EN2 (engrailed homeobox 2)
Diseases named in the same sentence as EN2 in open-access papers (continued):
Sharing a sentence is not in itself a finding about the gene and the disease.
ovarian carcinoma (5 papers, 2008 to 2025). A malignant neoplasm originating from the surface ovarian epithelium. "As the human engrailed homolog, EN2 has been reported to correlate closely with human cancers such as prostate, breast, bladder, ovarian cancer, and non -small cell lung cancer." (PMID 32732864, 2020). "Positive cytoplasmic EN2 staining was demonstrated in 78% of Epithelial ovarian cancers, with absence in normal ovary." (PMID 30285763, 2018). "We evaluated the expression of EN2 in Epithelial ovarian cancer, and reviewed its role as a biomarker." (PMID 30285763, 2018). "Conversely, in ovarian cancer, high EN2 expression predicts the adverse prognosis of the patients." (PMID 33685351, 2021). "The EN2 transcription factor is a novel ovarian cancer biomarker." (PMID 30285763, 2018). "Confirmatory immunohistochemical staining of three ovarian cancer tissue arrays was performed to confirm the findings in our patient cohorts, and again demonstrated high levels of EN2 protein staining in EOC cores, particularly the serous histological sub-type (data not shown)." (PMID 30285763, 2018). "EN2 was also detected in SAGE libraries derived from human brain glioblastoma, colon and ovarian carcinomas." (PMID 21566742, 2008). "As En2 expression had not previously been evaluated in ovarian cancer, we had little guide as to what constituted low or high expression, so we defined low expression as a CT value relative to ß-actin < 1000, and high expression as > 1000." (PMID 30285763, 2018).
Cognitive impairment (4 papers, 2012 to 2025). Abnormal cognition is characterized by deficits in thinking, reasoning, or remembering. "Abnormal cerebellar development, cognitive impairment, and E/I imbalance are observed in En2 KO mice and are relevant to ASDs, suggesting that disturbance of En2 expression is functionally linked to ASDs." (PMID 28809922, 2017). "Deletion of En2 in these structures may produce neurobiological changes that contribute to the cognitive deficits detected in En2 null mutant mice." (PMID 22829897, 2012). "Surprising in view of the elevated En-2 expression humans with ASD, mice lacking EN-2 also display ASD-like neurochemical alterations and behavioral phenotypes, including cognitive impairment and deficits in social interaction." (PMID 41149794, 2025).
Parkinson disease (4 papers, 2006 to 2024). A progressive degenerative disorder of the central nervous system characterized by loss of dopamine producing neurons in the substantia nigra and the presence of Lewy bodies in the substantia nigra and locus coeruleus. "mDA neurons from the Substantia Nigra (SN) and Ventral Tegmental Area (VTA) that die in Parkinson Disease (PD) express En1 and En2 in the adult and experience progressive mDA cell death in a En1+/- mouse line." (PMID 24396269, 2013). "In heterozygote animals (En1+/-;En2-/-), which are viable and fertile, postnatal maintenance of the nigrostriatal dopaminergic system is afflicted, leading to a progressive degeneration specific to this subpopulation and Parkinson's disease-like molecular and behavioral deficits." (PMID 19291307, 2009). "Mesencephalic dopaminergic (mDA) neurons that innervate the striatum and degenerate in Parkinson’s disease (PD) express both EN1 and EN2." (PMID 38550565, 2024). "The similarities to the disease etiology in combination with the nigral phenotype of En1+/-;En2-/- mice suggests that haplotype variations in the Engrailed genes and/or P75NTR that alter their expression levels could, in part, determine susceptibility to Parkinson's disease." (PMID 19291307, 2009). "Three of these genes (EN2, IREB2, and NGFB) are currently associated only with high level or general biological process categories that might or might not be related to Parkinson's disease." (PMID 16762065, 2006).
acute myeloid leukemia (3 papers, 2008 to 2023). Acute myeloid leukemia (AML) is a group of neoplasms arising from precursor cells committed to the myeloid cell-line differentiation. "Previous reports revealed that EN2 expression is deregulated in pediatric brain tumor and acute myeloid leukemia (AML)." (PMID 21566742, 2008).
epilepsy (3 papers, 2014 to 2023). A brain disorder characterized by episodes of abnormally increased neuronal discharge resulting in transient episodes of sensory or motor neurological dysfunction, or psychic dysfunction. "There were scarce literature published about the linkage between the EN2 mutations and epilepsy, although it may be expected because its theoretical relations with ASD." (PMID 30147646, 2018). "This evidence is in line with several studies carried out in several experimental models of ASD-epilepsy (Cntnap2, En2, Fmr1, Nrp2), in which defects of GABAA receptor-mediated neurotransmission have been related to the pathogenesis of ASD-epilepsy comorbidity." (PMID 37153775, 2023).
esophageal squamous cell carcinoma (3 papers, 2020 to 2024). Esophageal squamous cell carcinoma (ESCC) is a type of esophageal carcinoma (EC) that can affect any part of the esophagus, but is usually located in the upper or middle third. "EN2 also promotes the invasion and metastasis of esophageal squamous cell carcinoma by upregulating SPARC expression." (PMID 36061185, 2022). "However, the role of engrailed 2 (EN2), a member of the homeobox gene superfamily, in esophageal squamous cell carcinoma (ESCC) remains unknown." (PMID 32117645, 2020).
clear-cell renal cell carcinoma (2 papers, 2021). "For instance, in renal clear cell carcinoma and non-small cell lung cancer (NSCLC), EN2 expression is down-modulated and negatively linked to the clinicopathological stage." (PMID 33685351, 2021). "EN2 exerts a significant effect in many types of cancers, including breast, prostate, and epithelial ovarian cancers, in non-small cell lung cancers, and in clear-cell renal cell carcinoma." (PMID 33350453, 2021).
depression (2 papers, 2012 to 2019). "En2 null mutants displayed markedly higher levels of immobility on forced swim as compared to heterozygotes and wildtypes, suggesting a depression-related phenotype." (PMID 22829897, 2012). "Cognitive deficits on three tasks, a sensorimotor gating impairment, and a depression-related phenotype were seen in two independent cohorts of En2 null mutants, and in heterozygotes in some cases, as compared to wildtype littermates." (PMID 22829897, 2012). "Detection of a depression-related phenotype in En2 null mutants, which replicates and extends our initial finding, is notable in light of reports of depression in some autistic individuals." (PMID 22829897, 2012). "We further replicated our initial finding of a depression-relevant phenotype, which provides a functional read-out relevant to monoamine abnormalities in En2 null mutant mice." (PMID 22829897, 2012). "The neuroanatomical expression pattern of En2 found in our wildtype and mutant mice supports mechanistic hypotheses about anatomical disruptions in brain regions mediating social behaviors, cognitive abilities, depression-relevant behaviors, sensorimotor gating, and motor functions." (PMID 22829897, 2012).
melanoma (2 papers, 2018 to 2019). A malignant, usually aggressive tumor composed of atypical, neoplastic melanocytes. "This analysis demonstrated that EN2 protein was present in all of the EOC cell lines tested, in particular the paired platinum sensitive/insensitive cell lines, and the A375M melanoma cells, whilst it was not detectable in the normal skin fibroblast cell line." (PMID 30285763, 2018).
prostate tumors (2 papers, 2019 to 2021). "The secretion and uptake of EN2 protein suggests the possibility that normal prostate cells adjacent to prostate tumour cells could be exposed to sufficiently high levels of EN2 to change their transcriptional states." (PMID 30914795, 2019).
benign prostatic hyperplasia (1 paper, 2020). A non-cancerous nodular enlargement of the prostate gland. "In this study, to explore the application of EN2 in PC, we detected the immunohistochemical staining difference and EN2 expression level between benign prostatic hyperplasia (BPH) and PC." (PMID 32539763, 2020).
cerebellar ataxia (1 paper, 2022). A neurological syndrome characterized by clumsy and uncoordinated movement of the limbs, trunk, and cranial muscles. "Our method could also be easily employed with animal models of cerebellar defects and diseases, such as Cbln1-null mice, En2-null mice, and cerebellar ataxia mice, and allow for the fast screening of interventions or drug treatments in these disease models." (PMID 35741428, 2022).
cervical adenocarcinoma (1 paper, 2025). An adenocarcinoma arising from the cervical epithelium. "In addition, PT-PCR, immunohistochemistry, suggest that EN2 protein is overexpressed in endometrial cancer cell lines compared to cervical adenocarcinoma cells (P < 0.01)." (PMID 39607581, 2025).
chronic myeloid leukemia (1 paper, 2023). "The EN2 variant interacts with components of several archetypal kinase signaling events: ERBB, insulin, JAK and BCR-ABL (chronic myeloid leukemia) based on KEGG enrichment analysis, which also share downstream signaling with ERK/ELK and PI3K/AKT signaling and also with JNK/AP-1 and STAT." (PMID 37686522, 2023).
Currarino syndrome (1 paper, 2020). "Gene mutations involved in this condition include SHH, EN2, and HLXB9, which can be responsible for Pallister–Hall syndrome, Currarino syndrome, and Townes–Brocks syndrome, but are very rare." (PMID 33143152, 2020).
endometrial carcinoma (1 paper, 2025). A malignant tumor arising from the epithelium that lines the cavity of the uterine body. "The results suggest that the increase in EN2 protein content in cervical mucus may be caused by the high expression of endometrial cancer cells." (PMID 39607581, 2025). "The concentration of EN2 protein in cervical mucus can effectively identify endometrial cancer and precancerous lesions." (PMID 39607581, 2025). "In addition, HEC1B, KLE, and HeLa cell lines were used to characterize EN2 overexpression in endometrial cancer cells." (PMID 39607581, 2025). "It is still unknown whether the expression of EN2 protein in cervical mucus can be used as a non-invasive detection for endometrial cancer." (PMID 39607581, 2025). "This study aims to demonstrate that the EN2 protein in cervical mucus may serve as a novel biomarker for screening endometrial cancer." (PMID 39607581, 2025). "To evaluate the expression level of EN2 in endometrial cells, we selected the HEC-1-B (hormone related) type I endometrial cancer cell line and KLE type II endometrial cancer cell line for our study." (PMID 39607581, 2025). "To investigate the reasons for the increased expression of EN2 protein in cervical mucus, we selected endometrial cancer lesions from the same patient, endometrial tissue without endometrial cancer infiltration, and cervical tissue for the study." (PMID 39607581, 2025). "In clinical specimens, the expression level of EN2 protein in endometrial cancer tissues was significantly higher than that in endometrial tissues and cervical tissues without endometrial cancer infiltration." (PMID 39607581, 2025). "As the effect of age on EN2 protein is not yet clear, it is unknown whether EN2 protein measurement has the same efficacy for younger endometrial cancer patients." (PMID 39607581, 2025).
ependymoma (1 paper, 2022). A WHO grade II, slow growing tumor of children and young adults, usually located intraventricularly. "The SHH-2 gene signature comprised ALDH1A2 and EN2, which are involved in the organization of the hindbrain and upregulated in ependymoma PFA2 tumors, as well as the dopaminergic neuron markers FOXA1 and FOXA2." (PMID 35501487, 2022).
fragile X syndrome (1 paper, 2018). A genetic syndrome caused by mutations in the FMR1 gene which is responsible for the expression of the fragile X mental retardation 1 protein. "Besides high penetrance monogenic disorders like Fragile X Syndrome, prominent genes that have been identified include Reelin (RELN), MET, serotonin transporter (5HTT) and engrailed 2 (EN2)." (PMID 29691724, 2018).
Intellectual disability (1 paper, 2018). "In our study all the EN2-g patients suffered from some intellectual disability, ranging from severe to mild MR, in agreement to the described phenotype in 7q terminal deletion syndrome where EN2 gene is affected." (PMID 30147646, 2018).
keloid (1 paper, 2024). An irregularly shaped, elevated mark on the skin caused by deposits of excessive amounts of collagen during wound healing. "More recent genetic research has identified several genes, such as SMAD3, EN2, and NDFIP1, that may play crucial roles in keloid pathogenesis." (PMID 39119435, 2024).
lymph node metastasis (1 paper, 2020). "All these PC cases in our study were clinically diagnosed, and about 3/25 (12%) cases with low EN2 expression should be re-considered to avoid excessive medical treatment, since all these 3 PC patients with low EN2 expression had no lymph node metastasis and good prognosis after excision." (PMID 32539763, 2020).
pancreatic cancer (1 paper, 2026). "TCGA data further corroborated the significantly higher EN2 expression in pancreatic cancer tissues and showed that elevated EN2 levels are associated with poor overall survival." (PMID 42036759, 2026). "Immunohistochemical analysis of a pancreatic cancer tissue microarray revealed significantly elevated EN2 expression in tumour tissues compared with adjacent normal tissues." (PMID 42036759, 2026). "In this context, the present study is the first to identify a novel oncogenic role for Engrailed 2 (EN2) in the initiation and progression of pancreatic cancer and to characterise its underlying molecular pathogenesis." (PMID 42036759, 2026). "To define the biological significance of EN2, we investigated its role in promoting pancreatic cancer initiation and progression." (PMID 42036759, 2026). "Taken together, these findings identify EN2 as a critical driver of pancreatic cancer initiation, progression, and metastasis, representing the first report of its oncogenic function in this malignancy." (PMID 42036759, 2026). "Moreover, lentiviral-mediated shRNA knockdown of EN2 suppressed pancreatic cancer cell proliferation, invasion, and metastasis in vitro and significantly inhibited tumour growth in a xenograft mouse model, in part by inhibiting Notch signalling." (PMID 42036759, 2026).
renal carcinoma (1 paper, 2020). A carcinoma arising from the epithelium of the renal parenchyma or the renal pelvis. "However, decreased EN2 in renal carcinoma has been observed and downregulation of EN2 in 786-O cell line promoted proliferation and reduced apoptosis." (PMID 32158355, 2020).
serous ovarian cancer (1 paper, 2018). "En2 mRNA expression was elevated in serous ovarian tumours compared with normal ovary (p < 0.001), particularly in high-grade serous ovarian cancer (p < 0.0001) and in platinum-resistant tumours (p = 0.0232)." (PMID 30285763, 2018). "EN2 positive high-grade serous ovarian cancer patients had a shorter PFS (10 vs 17.5 months; p = 0.0103)." (PMID 30285763, 2018).
urothelial bladder cancer (1 paper, 2018). "Elevated levels of urinary EN2 have also been detected in patients with urothelial bladder cancer, with an overall sensitivity of 82% and specificity of 75%." (PMID 30285763, 2018). "A study of 226 patients with high grade urothelial bladder cancer showed that EN2 expression in cancer was strongly predictive of poor prognosis (manuscript in preparation)." (PMID 30285763, 2018).
viral infection (1 paper, 2019). "The relevance of EN2-induced MX2 expression in cells adjacent to the tumor is unclear, although it could be advantageous for the tumor to prevent viral infection of stromal cells that would otherwise generate a localized immune response." (PMID 30914795, 2019).
tumor (21 papers, 2008 to 2026). "The correlation between EN2 protein and the clinicopathological characteristics of patients was observed, which revealed that the expression level of EN2 was significantly associated with the tumor size, histological grade and TNM stage." (PMID 32732864, 2020). "Although no other relevant clinical associations with Gleason score or other tumor-related pathologic parameters were found in these cohorts (data not shown), in silico analysis using the Grasso cohort indicated that EN2 expression tends to be overexpressed in CRPC samples." (PMID 31500112, 2019). "The results indicated that the expression of EN2 in GBM tumour tissues was significantly higher than that in normal tissues." (PMID 40889210, 2025). "Overall, we found that high EN2 expression is not only a significant feature of GBM tumour tissues but also potentially serves as an important biomarker for guiding clinical decision‐making." (PMID 40889210, 2025). "Mechanistically, LINC00973 functioned as a molecular sponge for tumor-suppressive miR-6756-3p, consequently stabilizing transcription factor Engrailed-2 (EN2) mRNA and activating NOTCH pathway to promote HNSCC progression." (PMID 41419462, 2025). "The result indicated that the silence of EN2 observably inhibited tumour growth, leading to a marked reduction in both the tumour volume and weight in the nude mice." (PMID 40889210, 2025). "Subsequently, to validate the high expression of EN2 observed in the databases, we directly assessed EN2 expression levels in GBM tumour tissues using qRT‐PCR and Western blot." (PMID 40889210, 2025). "EN2 protein concentration in tumor tissue detected using ELISA was significantly higher than that in para-carcinoma tissues (P < 0.001)." (PMID 39607581, 2025). "In the future, we plan to carry out a large sample prospective clinical study to further confirm the threshold of EN2 protein concentration in cervical mucus and evaluate its sensitivity and specificity as an EC tumor biomarker." (PMID 39607581, 2025). "The mean cervical mucus EN2 concentration(573.9 ± 123.4 ng/mL) in the EC group significantly higher than benign lesion group(153.5 ± 106.2 ng/mL) and control group(53.0 ± 107.5 ng/mL) (P < 0.001)." (PMID 39607581, 2025). "The expression of miR-27b-3p and EN2 in the transplanted tumour further verified the targeted relationship between them, as indicated by luciferase assay." (PMID 33350453, 2021). "The high expression of EN2 is significantly correlated with tumor size, histological grade, advanced TNM stage as well as poor survival of patients." (PMID 32732864, 2020). "The results showed that EN2 expression was significantly higher in tumor tissues compared to the normal tissues." (PMID 32732864, 2020). "Our study found EN2 expression level was higher in CRC tissues than that in tumor adjacent tissues on the basis of GES9478, TCGA, and our CRC specimens." (PMID 32732864, 2020). "Since PTEN is a tumor suppressor protein proven in several tumors and VEGF is an inflammatory cytokine related to hyperplasia and tumor, EN2 has been confirmed to be positively related to the carcinogenesis of prostatic diseases." (PMID 32539763, 2020). "The results revealed that EN2 knockdown significantly reduced the tumor growth, as well as resulted in the decrease of both volume and weight of tumors." (PMID 32732864, 2020). "Specifically, previous reports showed that EN2 is overexpressed in tumor prostate tissues and PCa cell lines compared with normal prostate tissue and normal-like cell lines." (PMID 31500112, 2019). "EN2 was overexpressed in our two cohorts of PCa tissues compared to control and in tumor cell lines compared with normal-like prostate cells." (PMID 31500112, 2019). "The prevalence and expression pattern of EN2 was also assessed at the protein level in two separate cohorts of patient tumours which enabled the combined analysis of a large number of EOC specimens (111 HGSOCs in total)." (PMID 30285763, 2018).